TFEB (transcription factor EB)
Diseases named in the same sentence as TFEB in open-access papers (continued):
Sharing a sentence is not in itself a finding about the gene and the disease.
Hyperglycemia (6 papers, 2019 to 2025). An increased concentration of glucose in the blood. "In hyperglycemia-associated Phase I retinopathy mice, FGF21 (PF-05231023) decreased TFEB phosphorylation at serine 142, suggesting activation of the TFEB pathway by FGF21." (PMID 36943533, 2023). "Obese and diabetic conditions result in inactivation of TFEB and lysosomal protein degradation due to oxidative stress, suggesting hyperglycemia dysregulate the functions of mitochondria and lysosomes through inactivating TFEB." (PMID 35073330, 2022). "Consistent with human tissue, both LD formation and PLIN2 expression were enhanced in INS‐1 cells under hyperglycaemia, whereas TFEB activation and autophagy gene expression were significantly reduced." (PMID 30710421, 2019). "Hyperglycaemia lowered the expression of Tfeb, Lamp1, and Lc3, meaning that autophagy was down‐regulated at the transcriptional (TFEB), lysosomal (Lamp1) and autophagosome assembly (LC3) levels." (PMID 30710421, 2019). "Given that TFEB nuclear translocation and LAMP2 expression are suppressed in the islets of T2D, we hypothesized that hyperglycaemia and hyperlipidaemia may inhibit TFEB nuclear translocation and autophagy." (PMID 30710421, 2019). "Hyperglycemia may induce mitochondrial oxidative stress through 5’ AMP-activated protein kinase-independent pathways and inhibit transcription factor EB (TFEB), a critical transcription factor for lysosomal biogenesis and hydrolases." (PMID 35073330, 2022).
liver fibrosis (6 papers, 2013 to 2024). "Therefore, our data can find that anthocyanins can improve the blocked autophagic flux caused by liver fibrosis by regulating the expression of TFEB." (PMID 37324880, 2023). "A mouse hepatic stellate cell (HSC) model and a mouse liver fibrosis model were constructed to verify the expression of circ_0000623, miR‐351‐5p, and TFEB." (PMID 37324880, 2023). "In addition, we report for the first time that anthocyanins can inhibit liver fibrosis by promoting the expression of circ_0000623 to mediate the miR‐351‐5p/TFEB pathway to regulate changes in HSC autophagic flux." (PMID 37324880, 2023). "Anthocyanins could treat liver fibrosis by modulating circ_0000623/miR‐351‐5p/TFEB‐mediated changes in HSC autophagic flux." (PMID 37324880, 2023). "Therefore, we next investigated whether TFEB gene transfer reduces ATZ-induced liver fibrosis." (PMID 23381957, 2013). "Similarly, hepatocyte-specific overexpression of transcription factor EB (TFEB), a master regulator in autophagy and lysosomal biogenesis, is reported to reduce Z-AAT inclusion bodies and ameliorate liver fibrosis in Z-AAT transgenic mice." (PMID 34943844, 2021).
Pompe disease (6 papers, 2013 to 2021). "For Pompe disease, activation of TFEB has been suggested as a therapeutic target in order to increase the availability of autophagy-related proteins, and thus increase processing of intracellular waste and lysosomal content." (PMID 34120654, 2021). "Conversely, TFEB is inhibited and an autophagy is blocked in glycogen storage disease type II." (PMID 33732699, 2021). "According to the reports, overexpression of modulators of transcription factor EB (TFEB) in cultured myoblasts from a Pompe disease murine model reduced glycogen store and lysosomal size, facilitated autophagosome processing, and alleviated excessive accumulation of autophagic vacuoles." (PMID 32126021, 2020). "Since it has been shown that the curcumin analog C1 induces TFEB nuclear translocation in a mTORC1-independent manner, we could hypothesize that C1 may be beneficial in slowing the progression of Pompe Disease." (PMID 31412596, 2019). "TFEB and TFE3, which stimulate the expression of genes involved in autophagy and lysosome biogenesis, are a therapeutic target for Pompe Disease." (PMID 31412596, 2019). "The regulation of TFEB and TFE3 in skeletal muscle in general and in Pompe disease in particular remains an open question." (PMID 25183957, 2014).
pulmonary fibrosis (6 papers, 2019 to 2024). Chronic progressive interstitial lung disorder characterized by the replacement of the lung tissue by connective tissue, leading to progressive dyspnea, respiratory failure, or right heart failure. "Overexpression of the transcription factor TFEB reduced lysosomal dysfunction and silica-induced lung fibrosis." (PMID 35903328, 2022). "Pharmacological activation of TFEB using Torin 1 accelerates autophagic flux and significantly ameliorates bleomycin–induced pulmonary fibrosis." (PMID 30717487, 2019). "Our recent findings suggest that bleomycin can directly bind ANXA2 in lung epithelial cells to prevent the translocation of transcription factor EB (TFEB) into the nucleus, leading to TFEB inactivation and impeded autophagic flux, thereby inducing pulmonary fibrosis." (PMID 30717487, 2019). "In a BLM mouse model of pulmonary fibrosis, BLM binding with ANXA2 impedes transcription factor EB (TFEB)-induced autophagic flux; the inhibition of profibrotic cytokines induces autophagy flux and decreases the production of collagen to alleviate pulmonary fibrosis." (PMID 33671452, 2021).
Stroke (6 papers, 2023 to 2025). Sudden impairment of blood flow to a part of the brain due to occlusion or rupture of an artery to the brain. "Western blotting revealed that melatonin promoted TFEB nuclear translocation and autophagy in mice in the PT-Stroke + Mel group, evidenced by decreased cytoplasmic TFEB and p62 levels, as well as increased nuclear TFEB and LC3-II/LC3-I levels." (PMID 39940940, 2025). "Compared with the Sham group, cytoplasmic TFEB levels increased while nuclear TFEB levels decreased in the PT-Stroke group, suggesting the inhibition of TFEB nuclear translocation in mice with PT-stroke." (PMID 39940940, 2025). "Blocking TFEB or inhibiting AMPK nullified these protective effects, underscoring the significance of the AMPK-FOXO3a-TFEB pathway in exercise-mediated stroke protection." (PMID 40861274, 2025). "Specifically, TFEB nuclear translocation decreased in the cortex of mice with PT-stroke and SH-SY5Y cells exposed to acidic environments." (PMID 39940940, 2025). "More research will be needed to explore how TFEB regulates poststroke phagocytosis and how TFEB impacts brain injury repair via phagocytic mechanisms following stroke." (PMID 37601043, 2023). "Multiple known clinical pharmacological interventions modulate TFEB in stroke patients." (PMID 37491856, 2024). "In addition, remote ischemic preconditioning, a valuable strategy for protection against AIS, can ameliorate post-stroke outcomes by targeting TFEB." (PMID 37491856, 2024). "Moreover, drugs such as fenofibrate and aspirin, which target TFEB and PPAR-α, respectively, have also shown potential in stroke prevention and AD treatment by activating PPAR-α to upregulate TFEB and increase lysosomal biogenesis." (PMID 41457120, 2025). "However, it is currently not clear whether TFEB activation plays important roles in poststroke phagocytosis and thereby contributes to stroke pathology and outcomes by modulating the digestion of phagocytic cargos." (PMID 37601043, 2023).
synucleinopathy (6 papers, 2017 to 2024). A neurodegenerative disease that is characterized by the abnormal accumulation of aggregates of alpha-synuclein protein in neurons, nerve fibers or glial cells. "We next determined whether the neuroprotection associated with TFEB expression observed in PLP mice was also accompanied by a reduction of markers of synucleinopathy (i.e., our hypothesized primary target for enhanced ALP)." (PMID 31434803, 2019). "This suggests potential TFEB impairment at the early stages of cellular disease and underscores TFEB as a promising therapeutic target for synucleinopathies." (PMID 38581586, 2024). "Our observations support an important role for TFEB in the pathogenesis PD/DLB, thereby confirming the potential of targeting TFEB as a possible approach for urgently-required disease-modifying therapies for synucleinopathies." (PMID 38581586, 2024). "In dopaminergic neurons from the midbrains of (alpha)‐synucleinopathy models, TFEB overexpression or post‐translational hyperactivation downstream of mTORC1 rescues the aggregation of (alpha)‐synuclein, halting the progression of neuronal loss." (PMID 37728021, 2023). "Targeted overexpression of transcription factor EB (TFEB) decreases accumulation of α-synuclein and prevents neurodegeneration in animal models of synucleinopathies." (PMID 31434803, 2019). "Overall, we confirmed the relevance of targeting TFEB expression to enhance ALP as a promising therapeutic approach for all synucleinopathies." (PMID 31434803, 2019). "Because alteration of lysosomal integrity, and lysosomal membrane permeabilization especially, have been described in synucleinopathies, we next explored whether overexpression of TFEB could rescue lysosomal membrane permeabilization in PLP mice." (PMID 31434803, 2019). "However, no studies were performed so far to elucidate the role of the ALP in MSA pathogenesis and to exploit TFEB as a therapeutic target for this peculiar synucleinopathy." (PMID 31434803, 2019). "Here, we demonstrate that targeting neuronal expression of TFEB was sufficient to reduce synucleinopathy and prevent neurodegeneration in the A53T–α-syn rat model of PD, while only oligodendroglial overexpression of TFEB leads to neuroprotective effects in the MSA mouse model." (PMID 31434803, 2019). "This lack of efficacy of neuronal expression of TFEB in a MSA model could be due to the fact that, similar to the disease, neurons are less affected by the synucleinopathy compared with oligodendrocytes." (PMID 31434803, 2019).
B cell lymphomas (5 papers, 2020 to 2024). "TFEB moreover antagonizes malignant metabolic adaptation in Myc-driven B cell lymphomas, thereby suppressing uncontrolled cell growth." (PMID 39138218, 2024). "Transcription factor EB (TFEB) has been identified in a genome-wide CRISPR screen for genes regulating apilimod-induced cytotoxicity in B-cell non-Hodgkin lymphomas." (PMID 34625709, 2021). "MYC suppresses autophagy in B cell lymphomas by antagonizing the function of TFEB transcription factors, raising the possibility that PITPNC1 could control autophagy through MYC in LUAD and PDAC." (PMID 37210549, 2023). "Interestingly, although TFEB is an eIF5AHyp translation target in normal B cells (see Section 2.3.1), TFEB is transcriptionally suppressed in MYC overexpressing B cells, and is thus not detected as a target of eIF5AHyp in B-cell lymphoma." (PMID 39125743, 2024).
dementia (5 papers, 2016 to 2025). Loss of intellectual abilities interfering with an individual's social and occupational functions. "Together, these results suggest that optically regulated TFEB expression unlocks the potential of opto-therapeutics to treat AD and other dementias." (PMID 32208437, 2020). "In addition, trehalose has gained popularity as a putative anti-dementia supplement owing to its functions as an inducer of Transcription Factor EB (TFEB)-mediated autophagy, a mechanism suggested to contribute to the removal of protein waste such as beta amyloid or protein aggregates." (PMID 34578829, 2021).
Gaucher disease (5 papers, 2014 to 2025). Gaucher disease (GD) is a lysosomal storage disorder encompassing three main forms (types 1, 2 and 3), a fetal form and a variant with cardiac involvement (Gaucher disease - ophthalmoplegia - cardiovascular calcification or Gaucher-like disease). "Impaired autophagosome maturation accompanied with downregulation of TFEB and reduction of lysosomal gene expression were found in neurons differentiated from induced pluripotent stem cells of Gaucher disease patients." (PMID 32854299, 2020). "The authors proposed that glycosphingolipid accumulation in Gaucher disease leads to increased mTORC1 activity, which in turn results in increased TFEB phosphorylation." (PMID 32854299, 2020).
glioma (5 papers, 2022 to 2026). A benign or malignant brain and spinal cord tumor that arises from glial cells (astrocytes, oligodendrocytes, ependymal cells). "Therefore, we sought to validate the potential association and functionality of NURP1/KDM3A/TFEB in the context of TMZ resistance in glioma cells." (PMID 37305393, 2023). "Immunoblotting and immunohistochemistry of human glioma samples of different stages also showed that the expression of TFEB in human glioma specimens increased as the degree of glioma malignancy increased." (PMID 38356708, 2024). "Third, we discussed that autophagy can promote the migration of glioma cells by activating p38 to regulate TFEB-mediated autophagy." (PMID 38356708, 2024). "The data show that a p38 inhibitor can affect TFEB function and then affect the migration of glioma cells." (PMID 38356708, 2024). "According to the online website of the China Glioma Genome Atlas Project, the expression of TFEB in GBM was significantly higher than that in LGG." (PMID 38356708, 2024). "In summary, our results show that MCU regulates TFEB-mediated autophagy and promotes the migration of glioma cells through p38." (PMID 38356708, 2024). "By investigating the potential association and roles of NURP1/KDM3A/TFEB, we aim to provide new insights into the molecular route of TMZ resistance in glioma cells." (PMID 37305393, 2023). "Collectively, these findings support the role of NUPR1 in promoting cell autophagy to reduce TMZ resistance in glioma in vivo via the KDM3A/TFEB axis." (PMID 37305393, 2023). "In this study, we evaluated the effects of nuclear protein-1 (NURP1) on TMZ resistance in hypoxia-treated glioma cells by modulating autophagy via the KDM3A/TFEB axis." (PMID 37305393, 2023). "Altogether, our findings suggest that TFEB overexpression partially restores glioma cell autophagy repressed by silencing NURP1." (PMID 37305393, 2023). "For a comprehensive understanding of the effector of the KDM3A/NURP1 axis in glioma cell autophagy, it is vital to consider the role of TFEB in mediating the autophagy-lysosome system in various tumors." (PMID 37305393, 2023). "Furthermore, p38 promotes glioma progression by activating Transcription Factor EB (TFEB)-mediated autophagy." (PMID 38356708, 2024). "Thus, MCU promotes glioma cell migration by activating autophagy in a p38/TFEB pathway-dependent manner, which provides a theoretical basis for new therapeutic targets for gliomas." (PMID 38356708, 2024). "Additionally, p38 promoted glioma progression through autophagy mediated by transcription factor EB (TFEB)." (PMID 38632642, 2024). "However, in a bioinformatics search and immunohistochemical analysis of human glioma samples, the autophagy level and TFEB increased with the malignant degree of glioma." (PMID 38356708, 2024). "Moreover, the overexpression of KDM3A or TFEB promoted glioma cell autophagy." (PMID 37305393, 2023). "This is due to the evidence that NUPR1 promotes glioma cell autophagy and TMZ resistance via the KDM3A/TFEB axis." (PMID 41596413, 2026). "In essence, our experimental findings validated that NUPR1 binding to KDM3A reduces H3K9me2 levels and enhances TFEB transcription, leading to increased autophagy and augmenting TMZ resistance in hypoxia-treated glioma cells." (PMID 37305393, 2023). "Our results suggest that hypoxia-induced NUPR1 promotes TFEB transcription by binding to KDM3A and reducing H3K9me2 levels, thereby augmenting glioma cell autophagy and TMZ resistance." (PMID 37305393, 2023). "Overall, our findings highlight a mechanism by which NUPR1 enhances glioma cell autophagy and TMZ resistance via the KDM3A/TFEB axis." (PMID 37305393, 2023). "In conclusion, the present study aims to investigate the potential regulatory role of NURP1 may regulate the KDM3A/TFEB axis to modulate autophagy under hypoxia, and this process may affect TMZ resistance in glioma cells." (PMID 37305393, 2023).
mucolipidosis type IV (5 papers, 2019 to 2021). A lysosomal disease characterized by psychomotor delay, progressive visual impairment, and achlorhydria. "The effects of Rap and Tem on TFEB nuclear translocation were abolished in Mucolipidosis IV (ML1−/−) human fibroblasts or by ML-SI3." (PMID 31112550, 2019). "Mucolipidosis, Type IV (MLIV) is caused by mutations in MCOLN1 (Mucolipin 1), an endo-lysosomal pH sensitive channel that facilitates diffusion of monovalent and divalent ions and facilitates lysosomal and autophagic regulation via its interaction with TFEB and mTOR signaling." (PMID 32351971, 2020). "Indeed, cells from Mucolipidosis type IV (MLIV) patients show a delayed fusion of autophagosomes with late endosomes/lysosomes and alterations in TFEB shuttling." (PMID 33859333, 2021). "However, TFEB overexpression failed to induce cellular clearance in a mucolipidosis IV model characterized by mutations in the MCOLN1 gene, suggesting that TFEB-mediated lysosomal exocytosis and clearance may occur through the activation of the Ca2+ channel TRPML1." (PMID 32276321, 2020).